STOX1 (storkhead box 1)
Description:
Involved in regulating the levels of reactive oxidative species and reactive nitrogen species and in mitochondrial homeostasis in the placenta. Required for regulation of inner ear epithelial cell proliferation via the AKT signaling pathway (By similarity). [Isoform A]: Involved in cell cycle regulation by binding to the CCNB1 promoter, up-regulating its expression and promoting mitotic entry. Induces phosphorylation of MAPT/tau.
Synonyms: C10orf24; FLJ25162
Tractability: PROTAC: ubiquitination databases record sites on it.
Gene: Protein-coding gene on chromosome 10 (68,827,199 to 68,895,432, forward strand). Ensembl gene ENSG00000165730.
Subcellular location: Cytoplasm (Isoform A); Nucleus; Cytoplasm, cytoskeleton, microtubule organizing center, centrosome; Nucleus (Isoform B); Nucleus, nucleolus (Isoform C)
Subcellular location (Human Protein Atlas): Nucleoplasm; Cytosol; Nucleoli fibrillar center
Gene Ontology:
Molecular function: protein binding; RNA polymerase II transcription regulatory region sequence-specific DNA binding; DNA-binding transcription factor activity
Biological process: cellular response to nitrosative stress; negative regulation of gene expression; positive regulation of cyclin-dependent protein kinase activity; positive regulation of G1/S transition of mitotic cell cycle; positive regulation of G2/M transition of mitotic cell cycle; positive regulation of gene expression; positive regulation of peptidyl-serine phosphorylation; positive regulation of peptidyl-threonine phosphorylation; regulation of gene expression; regulation of mitochondrial DNA metabolic process; regulation of mitochondrial membrane potential; regulation of mitochondrion organization; regulation of response to oxidative stress; regulation of transcription by RNA polymerase II; inner ear development; positive regulation of cell cycle; positive regulation of otic vesicle morphogenesis; positive regulation of phosphatidylinositol 3-kinase/protein kinase B signal transduction; regulation of mitotic cell cycle
Cellular component: centrosome; cytoplasm; cytosol; fibrillar center; nucleoplasm; nucleus; cell cortex; nucleolus
Genetic constraint (gnomAD): Loss-of-function variants: 57 observed, 76.18 expected, observed/expected ratio (o/e) 0.75, 90% interval 0.6 to 0.93. The upper end of that interval is the gene's LOEUF score, 0.93, which puts it in group 3 of 6, group 1 being the genes least tolerant of losing a copy. Missense variants: 970 observed, 1,126.7 expected, observed/expected ratio (o/e) 0.86, 90% interval 0.82 to 0.91. Synonymous variants: 355 observed, 398.75 expected, observed/expected ratio (o/e) 0.89, 90% interval 0.81 to 0.97.
Homologues: Orthologues: macaque STOX1 (95% identical), chimpanzee STOX1 (89% identical), pig STOX1 (76% identical), dog STOX1 (71% identical), rabbit STOX1 (71% identical), guinea pig STOX1 (71% identical), mouse Stox1 (61% identical), rat Stox1 (59% identical), tropical clawed frog stox1 (41% identical), zebrafish stox1 (33% identical), Drosophila melanogaster ko (17% identical), Caenorhabditis elegans ham-1 (10% identical). Paralogues in human: STOX2 (24% identical).
Diseases named in the same sentence as STOX1 in open-access papers:
STOX1 is named in the same sentence as 26 diseases in open-access papers, as found by Europe PMC text mining. Sharing a sentence is not in itself a finding about the gene and the disease. The quoted sentences say what the papers report.
preeclampsia (31 papers, 2008 to 2025). Preeclampsia is a hypertensive disorder of pregnancy that is characterized by new-onset hypertension with proteinuria presenting after 20 weeks of gestation, and depending on mild or severe forms may initially present with severe headache, visual disturbances, and hyperreflexia. "Initially, STORKHEAD_BOX1 PROTEIN 1 (STOX1) was recognized as a potential gene with an increased risk of developing preeclampsia." (PMID 40968268, 2025). "This study aims to investigate the potential association between the STOX1:p.(Tyr153His) variant (rs1341667) and the development of preeclampsia among pregnant Egyptian women." (PMID 40968268, 2025). "Specific STOX1 gene variants have been associated with an increased risk of preeclampsia, revealing an important role in the development and function of the placenta." (PMID 39123689, 2024). "In accordance with our results, we propose an additional aspect to the role of STOX1 in increasing the risk of preeclampsia through the regulation of immune suppression." (PMID 36555567, 2022). "Mutations within STOX1 have been associated to preeclampsia, a pathology of pregnancy characterized by high blood pressure and signs of damage to other organ system that can be lethal for the mother and for the fetus." (PMID 35460423, 2022). "The importance of STOX1 variants in preeclampsia was initially shown among Dutch familial cases, and also recently in the Turkish population." (PMID 36555567, 2022). "To validate RAS activation as the mechanism underlying gestational hypertension in Stox1-KO mice, we treated pregnant mice with the Ang II receptor blocker (ARB) losartan." (PMID 33301424, 2021). "In 2005, van Dijk and colleagues linked the gene encoding the Storkhead-box protein 1 transcription factor (STOX1) to preeclampsia and gestational hypertension in Dutch families." (PMID 33301424, 2021). "The authors reported a common, maternally inherited single nucleotide variant, Y153H, predicted to alter the function of the DNA-binding domain, and proposed that loss of STOX1 function in the placenta was the underlying cause of preeclampsia in their cohort." (PMID 33301424, 2021). "To investigate the molecular mechanisms underlying the Stox1-KO phenotype, we examined the placental expression of genes previously implicated in preeclampsia pathogenesis." (PMID 33301424, 2021). "Our data show that STOX1 loss of function in mice causes gestational hypertension resulting from uteroplacental RAS activation, which is reversed with ARB therapy." (PMID 33301424, 2021). "For instance, the overexpression of storkhead box 1, a preeclampsia-related gene, was associated with the hyperactivation of mitochondria, resulting in increased free radicals in the placenta." (PMID 32392703, 2020). "Many earlier studies have identified that STOX1 was found to be the first gene associated with preeclampsia susceptibility." (PMID 31724315, 2020). "Another transcription factor, Stox1, was upregulated in TGCs (2.93-fold increase); its loss of function is associated with preeclampsia in a large cohort of Dutch females indicating the significance of the elevated expression in TGCs." (PMID 32762732, 2020). "The STOX1 gene is implicated as a genetic factor linked to the placental-based disease of preeclampsia in humans." (PMID 26588211, 2015). "In other words, the genotype linked to preeclampsia, that is, STOX1 Y153H, has a demonstrated effect on extravillous trophoblast invasion, central in the etiology of preeclampsia." (PMID 21490791, 2011). "The Dutch patients associated with STOX1 turned out to be phenotypically homogenous as defined by familial early-onset preeclampsia with an abnormal placental development complicated by IUGR." (PMID 21490791, 2011). "The importance of the STOX1 preeclampsia susceptibility gene, as discovered in 2005 in Dutch females, was initially challenged." (PMID 21490791, 2011).
preeclampsia (continued). "The preeclamptic families with linkage to 10q22 and associated with STOX1 were a phenotypically homogenous patient cohort suffering from familial severe early-onset preeclampsia complicated by IUGR." (PMID 21490791, 2011). "Mutations in STOX1 were proposed to be causal for predisposing to preeclampsia, a hypertensive disorder originating from placental defects affecting up to 10% of human pregnancies." (PMID 19079545, 2008). "Finally, a recent promoter variant of STOX1 (−922T>C) was associated with an increased risk of preeclampsia." (PMID 38439971, 2024). "The STOX1 gene has been shown to cause placental dysfunction, which may be the center of the common pathway leading to preeclampsia." (PMID 35464758, 2022). "Storkhead-box protein 1 (STOX1) was first identified as a preeclampsia risk gene through family-based genetic linkage studies in which loss-of-function variants were proposed to underlie increased preeclampsia susceptibility." (PMID 33301424, 2021). "This analysis provides functional data supporting the hypothesis that mutations affecting STOX1 function may predispose women to developing preeclampsia." (PMID 33301424, 2021). "There are many preeclampsia-like mouse models associated with the renin-angiotensin system, ephrin B2, or storkhead box 1, but the role of autophagy in these models is entirely unknown." (PMID 32392703, 2020). "STOX1 encodes for a DNA binding protein involved in preeclampsia." (PMID 31065004, 2019). "Furthermore, recent work in a transgenic murine model overexpressing storkhead box 1 (preeclampsia susceptibility gene) showed exaggerated placental mitochondrial activity." (PMID 27604418, 2016). "The STOX1 gene is a key player in trophoblast dysfunction underlying early-onset preeclampsia." (PMID 24991435, 2014). "Rather than providing a complete overview of all aspects of preeclampsia, we provide a focused overview by summarizing and discussing the latest data on the role of the STOX1 as a key player in trophoblast dysfunction underlying familial early-onset preeclampsia with growth retardation." (PMID 21490791, 2011). "However, the latest data including those from independent groups not only confirm the role of STOX1 in trophoblast dysfunction underlying preeclampsia but also indicate a role for its paralog, STOX2." (PMID 21490791, 2011). "STOX1, however, is only one of the genes that give susceptibility for preeclampsia." (PMID 21490791, 2011). "In addition, they strongly suggest that anomalies in STOX1 expression are associated with the onset of preeclampsia, thus indicating that this gene should be the target of future studies." (PMID 19079545, 2008). "Supporting the hypothesis that conservation of piRNA expression across ~100 million years of Eutherian evolution implies function, we determined that one ECpiC locus generates abundant piRNAs antisense to the STOX1 transcript, a gene clinically associated with preeclampsia." (PMID 26588211, 2015). "Previous studies on STOX1 have primarily focused on its involvement in non‐cancerous conditions such as Alzheimer's disease, preeclampsia, and trophoblast dysfunction." (PMID 40567110, 2025). "Future studies with larger, well characterized cohorts, stratification by disease severity and onset, and multi variant analyses will be essential to better define the role of STOX1 in preeclampsia pathogenesis." (PMID 40968268, 2025). "In 2005, STOX1 (Storkhead bOX 1) was discovered as the first gene involved in genetic forms of preeclampsia in Dutch families." (PMID 38439971, 2024). "The involvement of STOX1 in preeclampsia was further substantiated by the creation of transgenic mice overexpressing the human protein in the feto-placental unit, which recapitulate the human symptoms of the disease." (PMID 38439971, 2024). "One of the most notable variants, Y153H, was first identified in a study that established the connection between STOX1 and preeclampsia." (PMID 38439971, 2024).
preeclampsia (continued). "As such, in the STOX1 mouse model of preeclampsia, we have shown previously that oxidative/nitrosative stress is a major cause of the onset of the disease, corroborating the importance of this pathway in hypertensive disorders of pregnancy." (PMID 35052610, 2022). "Recently, it was revealed by exome sequencing that there are rare variants of STOX1 associated with HELLP syndrome, a preeclampsia subtype with serious hepatic complications." (PMID 36555567, 2022). "We overexpressed the STOX1 A/B transcription factor gene that was discovered in familial forms of preeclampsia in immortalized placental cell lines." (PMID 36555567, 2022). "Our model was the immortalized placental-derived BeWo and JEG-3 cell lines that overexpress the STOX1 A/B transcription factor gene that was discovered in familial forms of preeclampsia." (PMID 36555567, 2022). "Pregnant Stox1-KO mice developed gestational hypertension evidenced by a significant increase in blood pressure compared with WT by E17.5." (PMID 33301424, 2021). "Mechanistically, we found that gestational hypertension in Stox1-KO mice resulted from activation of the uteroplacental renin-angiotensin system." (PMID 33301424, 2021). "For example, deregulation of alternative splicing of the gene STOX1, involved in preeclampsia and Alzheimer's disease induces a disequilibrium of its two isoforms and increases the risk of disease." (PMID 33433680, 2021). "STOX1 has also been studied using a transgenic mouse model in which placental overexpression of human STOX1 induces a preeclampsia-like phenotype." (PMID 33301424, 2021). "For example, a variant in NODAL, a member of the transforming growth factor–β superfamily required for proper trophoblast differentiation and fetal growth in mice, resides in the same linkage area as STOX1 and segregates with Y153H in familial preeclampsia." (PMID 33301424, 2021). "One study investigating the transcriptional targets of STOX1, for example, revealed specific patterns of gene expression in STOX1-overexpressing choriocarcinoma cells that mirror those in preeclampsia." (PMID 33301424, 2021). "The STOX1 transgene mouse model provides a useful model for analysing in depth and in an organ-targeted way the pathophysiological consequences of preeclampsia." (PMID 31189914, 2019). "In this study, RNA-seq analysis revealed endothelial transcriptome alterations in the STOX1 mouse model of preeclampsia." (PMID 26758611, 2016). "The objective of the present study is to evaluate the cardiovascular dysfunction induced by preeclampsia by examining the endothelium of mice suffering of severe preeclampsia induced by STOX1 overexpression." (PMID 26758611, 2016). "For example, transcription factor STOX1 overexpressing pregnant mice exhibit symptoms of severe pre-eclampsia: gestational hypertension, proteinuria, and elevated plasma levels of sVEGFR-1 (soluble fms-like tyrosine kinase 1) and sEng." (PMID 25303561, 2015). "The STOX1 gene, the ERAP1 and 2 genes, the syncytin envelope gene, and the −670 Fas receptor polymorphisms are involved in the development of preeclampsia." (PMID 24991435, 2014). "The STOX1 gene, which is placentally expressed, was identified as a candidate gene for preeclampsia (n = 157) in a Dutch population." (PMID 24991435, 2014). "Currently, only two preeclampsia susceptibility genes (ACVR2A, STOX1) have been identified within confirmed regions with significant genome-wide linkage, although many genetic screens in multiple populations have been performed." (PMID 21490791, 2011). "The correlation between these studies was found to be highly significant looking at genes affected by STOX1- and preeclampsia-modified genes." (PMID 21490791, 2011). "In conclusion, our study indicates that STOX1 deserves further investigation for its role in the aetiology of preeclampsia." (PMID 19079545, 2008).
preeclampsia (continued). "In the present study, we show in a cellular model that STOX1 overexpression reproduces the transcriptional effects of preeclampsia in the human placenta." (PMID 19079545, 2008). "Our results contribute to reconcile contradictory data concerning the involvement of STOX1 in preeclampsia." (PMID 19079545, 2008). "Our results show that STOX1 regulates gestational hypertension through mechanisms involving the RAS and demonstrate the utility of genetic mouse models for uncovering links between genetic variants and pathways implicated in the pathogenesis of hypertensive disorders of pregnancy." (PMID 33301424, 2021). "By mating wildtype (wt) females with STOX1 transgenic males, the transgene expression is restricted to the fetoplacental unit, making this one of the few animal models representing a severe and early onset form of preeclampsia." (PMID 31189914, 2019). "The STOX1 mice could help to better understand the endothelial dysfunction in the context of preeclampsia, and guide the search for efficient therapies able to protect the maternal endothelium during the disease and its aftermath." (PMID 26758611, 2016). "Only two preeclampsia susceptibility genes have been identified so far, ACVR2A and STOX1." (PMID 21490791, 2011). "Furthermore, villous explants homozygous for the STOX1 H-allele associated with preeclampsia have a reduced trophoblast outgrowth and an induced responsiveness of CTNNA3 expression upon STOX1 expression." (PMID 21490791, 2011). "Therefore, although JEG-3 cells were used with STOX1 overexpression to induce effects, the outcomes are comparable to physiological changes found in preeclampsia samples, justifying the microarray results obtained." (PMID 21490791, 2011). "Our results provide new data suggesting that STOX-1 could be involved in the processes leading to preeclampsia." (PMID 19079545, 2008). "The preeclampsia mouse model used in the in vivo study substantiated the evidence that overexpression of the Stox1 gene in the placenta induces the development of PE symptoms and brought new evidence of the direct influence of the STOX1 on the pregnancy outcome." (PMID 39817714, 2025). "Other potentially deleterious variants of STOX1 have been identified in a whole-exome sequencing study carried out in Colombian patients affected by the HELLP (hemolysis, elevated liver enzyme, low platelet) syndrome, a severe multi-organ complication of preeclampsia." (PMID 38439971, 2024). "Interestingly, as a comparable function to STOX1, which shows a gain-of-function is suggested, and STOX2 is downregulated in preeclampsia samples, compatible with a loss-of-function, this would indicate that these two genes have similar functions but opposite effects in placental function." (PMID 21490791, 2011). "Since STOX1 suppresses CD24 which confers immune tolerance, this study indicates that there is an additional pathway for STOX1 involvement in the development of preeclampsia." (PMID 36555567, 2022). "In the Storkhead box 1 (STOX1) preeclampsia mouse model, pregnant females develop severe and early onset manifestations as seen in human preeclampsia e.g. gestational hypertension, proteinuria, and organ alterations." (PMID 31189914, 2019). "Hypoxia-induced genes were nevertheless found elevated in preeclampsia, and were significantly correlated with gene-induction in the JEG-3 cells overexpressing STOX1 (present study)." (PMID 19079545, 2008). "We show that pregnancies resulting from breeding of homozygous Stox1-KO mice develop gestational hypertension, without overt signs of preeclampsia." (PMID 33301424, 2021). "Stox1-KO mice lacked overt signs of preeclampsia, despite evidence of placental hypoxia, and developed hypertension late in gestation associated with abnormal placental extracellular matrix deposition and increased decidual vascularization." (PMID 33301424, 2021).
preeclampsia (continued). "Two studies (2007) in both a Dutch and a Finnish population did not support or confirm that the STOX1 gene was involved in development of preeclampsia." (PMID 24991435, 2014). "In contrast, the Stox1-KO phenotype was driven by endogenous upregulation of renin, which would not be expected to have as striking a phenotype because of the presence of intact blood pressure and RAS regulatory mechanisms, and is more consistent with human gestational hypertension." (PMID 33301424, 2021). "We show that without further manipulation, STOX1 overexpression by the feto-placental unit induces cardiovascular dysfunction, suggesting that this model is a handy tool for understanding the systemic endothelial dysfunction in preeclampsia and testing therapies, to improve maternal health." (PMID 26758611, 2016).